EGFR (epidermal growth factor receptor)
Diseases named in the same sentence as EGFR in open-access papers (continued):
Sharing a sentence is not in itself a finding about the gene and the disease.
Pleural effusion (continued). "Such a result is compatible with the notion that RNA-sequencing is more sensitive than direct-sequencing (using DNA) because of the natural enrichment of the mutant EGFR mRNA in the cells of pleural effusion." (PMID 27352172, 2016). "We thus processed both pleural effusions and treated the cultured cells with the EGFR TKI erlotinib." (PMID 27548442, 2016). "EGFR mutations of NSCLC patients can be detected using plasma and pleural effusion samples, which provides a noinvasive method to predict the efficacy of gefitinib in advanced NSCLC." (PMID 20843324, 2010). "The PCR–SSCP method can be theoretically applied not only to resected tumour samples but also to sputum, pleural effusion, and biopsy specimens; as such, this technique can be used to preselect appropriate patients for EGFR tyrosine kinase inhibitor treatment." (PMID 16052218, 2005). "Utilizing the Clariom D Human Chip technology, the expression patterns of lncRNAs in pleural effusions were examined in three patients with EGFR mutations and three patients without EGFR mutations." (PMID 39324002, 2024). "Next-generation sequencing (NGS) reported EGFR L858R mutation in exon 21 (frequency: 10%), and EGFR T790M mutation in exon 20 (frequency: 2.7%) in pleural effusion, but not in plasma." (PMID 38996163, 2024). "Case #316: In the present case, pleural effusion was observed at diagnosis and a reduction in tumor size (from 1.5 cm to 1.2 cm, a 10% decrease in tumor size) was observed after administration of afatinib targeting an EGFR exon 19 deletion." (PMID 38773241, 2024). "Moreover, first‐ and second‐generation EGFR‐TKIs have demonstrated poor effectiveness in cases of pleural effusion." (PMID 38226415, 2024). "In patients with EGFR WT genotype (Patients 11, 2, and 13), the gross photography of pleural effusions after arsenic intrapleural administration showed a significant reduction in the volume of the pleural effusion and the number of clusters of the tumor cells." (PMID 37371816, 2023). "Of the 108 effusion samples, 103 (95.4%) were pleural effusions and 5 (4.6%) were ascites, and 12, 87, and 9 samples (11.1%, 80.6%, and 8.3%) were obtained before EGFR–TKI treatment, after 1 EGFR–TKI treatment session, and after 2 or more EGFR–TKI treatment failures, respectively." (PMID 35141163, 2022). "In contrast to the left pleural effusion, EGFR exon 20 T790M might have mediated the acquired resistance in lesions in the right lung of this patient." (PMID 35872785, 2022). "Among patients with squamous, univariate analyses showed that the EGFR mutation rate was significantly higher in females (P = 0.004), without a smoking history (P = 0.049), and pleural effusion (P = 0.032)." (PMID 31144459, 2019). "The mean mRNA value of IGFBP7 expression in cancer cells isolated from treatment-naïve pleural effusions (n = 8) (0.114 ± 0.059) was significantly lower than that after acquired resistance to EGFR-TKI treatment (n = 16) (1.18 ± 0.412; p = 0.0212, by Student’s t-test)." (PMID 30609749, 2019). "These patients presented with pneumonopathy and pleural effusion, which differ from the pulmonary symptoms observed with conventional EGFR-TKIs (diffuse alveolar damage), and the possibility of TAS-121 causing pulmonary capillary leak-like symptoms was suggested." (PMID 30790152, 2019). "Two out of 15 patients with pleural effusions had negative blood tests for the sensitizing EGFR mutations." (PMID 31602787, 2019). "IHC result showed that EGFR is positively stained in pleural effusion pellet." (PMID 30425968, 2018). "In our study, EGFR genotyping using EV-derived DNA and cfDNA from the supernatant of pleural effusions in patients who were either EGFR-TKI naïve or who acquired resistance to EGFR-TKI showed good agreement with tissue EGFR genotyping (κ =0.861, 0.810, 1.0, 0.885)." (PMID 30526536, 2018).
Pleural effusion (continued). "Furthermore, EGFR genotyping using EV-derived DNA from the supernatant of pleural effusions showed 100% agreement with tissue EGFR genotyping (κ = 1.0; p = 0.000)." (PMID 30526536, 2018). "No more than one mutation was identified per patient, and no EGFR mutations were detected in pleural effusion fluid that did not contain malignant cells." (PMID 17060940, 2006). "The lack of pathological quality control standard in detecting epidermal growth factor receptor (EGFR) gene mutation in malignant pleural effusion leads to confusion in the interpretation of detection results and the clinical use of EGFR-tyrosine kinase inhibitor (TKI)." (PMID 33357312, 2020). "Unfortunately, we have no data at the present time on whether EGFR mutations were detectable in pleural effusion samples with either a few malignant cells, a small proportion of malignant cells with normal mesothelial cells, or cytologically negative samples." (PMID 17060940, 2006). "Following the failure of first‐generation EGFR‐TKI therapy, the sites of rebiopsy mainly included the lung, lymph nodes, and pleural effusion." (PMID 39741120, 2025). "Although the literature on this subject is limited, tumor alterations, mainly in the EGFR and KRAS genes, have been detected in EV-derived DNA from biofluids such as plasma, pleural effusion, and cerebrospinal fluid." (PMID 39684756, 2024). "As next we evaluated our targeted EGFR, KRAS and BRAF test results from cfDNA obtained from pleural effusion and blood and from gDNA isolated from sediment cell blocks and lung biopsies." (PMID 34257581, 2021). "We observed the same trend as we did in the pleural effusions, namely, significant upregulation of SCARNA7, MALAT1, and NONHSAT017369 in the EGFR‐mutant group compared to the EGFR wild‐type group (P < 0.05)." (PMID 31691525, 2020). "Eighteen patients displayed acquired resistance to EGFR-TKI, who developed pleural effusion after TKI treatment." (PMID 30526536, 2018). "From 32 patients who were EGFR-TKI naïve and 18 who acquired EGFR-TKI resistance, the concentrations of EV-derived DNA and cfDNA from the supernatant of pleural effusions were measured by NanoDrop spectrophotometry." (PMID 30526536, 2018). "Of the 50 patients, 32 were EGFR-TKI naïve and presented pleural effusion at the time of diagnosis or after treatment failure." (PMID 30526536, 2018). "We established cell culture models from biopsies or pleural effusions of NSCLC patients whose disease progressed on treatment with a first- and/or second-generation EGFR or ALK TKI and responded to a second- or third-generation inhibitor." (PMID 29241554, 2017). "Pleural effusion was significantly less common among KRAS-positive patients, compared to EGFR-positive patients or ALK-positive patients (p = 0.046 and p = 0.026, respectively)." (PMID 27518729, 2016). "Pleural effusion was significantly less common among KRAS-positive patients, compared to EGFR-positive patients and ALK-positive patients (p = 0.046 and p = 0.026, respectively)." (PMID 27518729, 2016). "However, in the multivariate analysis, the presence of the EGFR gene mutation was independently associated with female sex (OR: 3.873; 95% CI 1.084–13.836, p = 0.04) and the absence of smoking (OR: 5.105; 95% CI 1.363–19.120, p = 0.02), but not with the presence of pleural effusion." (PMID 39596989, 2024). "The molecular retesting of the tumour cells obtained from the recurrent pleural effusion revealed the absence of the ROS1 translocation, whereas the EGFR and HER2 mutations were still present." (PMID 38891886, 2024). "In conclusion, the intrapleural administration of arsenic was able to reduce the amount of the pleural effusion, lighten the color of the pleural effusion, and diminish the number of tumor cells in the pleural effusion in NSCLC patients with various EGFR genotypes." (PMID 37371816, 2023).
Pleural effusion (continued). "The tumor cells in the pleural effusion were all negative for immunohistochemical markers (TTF-1 and Napsin A) and lung-specific oncogenic driver alterations (EGFR mutation and ALK translocation)." (PMID 30634950, 2019). "Unfortunately, most patients who initially had mutant EGFR in NSCLC without pleural effusion develop resistance to the prescribed therapy within a year." (PMID 31443309, 2019). "When using cfDNA from the supernatant of pleural effusions for EGFR genotyping, 17 out of 18 patients displayed agreement with the tissue EGFR genotyping, whereas one patient did not exhibit agreement (94% agreement, κ = 0.885; p = 0.000)." (PMID 30526536, 2018). "The most sensitive method for EGFR and ALK testing might be true only when the testing specimen is pleural effusion." (PMID 27352172, 2016). "It was believed that mutant EGFR mRNA from tumor cells was enriched in the RNA samples from pleural effusions because the non-tumor cells produced little wild-type EGFR mRNA." (PMID 27352172, 2016). "Our study suggests thatthe mPFS and mOS for EGFR-TKI therapy is different between different sampletypes, and the prognosis of the tissue sample delivery population is significantlybetter than that of the liquid biopsy and pleural effusion cytology deliverypopulations." (PMID 37881485, 2023). "These indicators include the clinical parameters such as ECOG PS, non-adenocarcinoma histology, EGFR mutation and LENT score, the serum indicators such as NLR, hemoglobin, total protein, albumin, LDH, CRP and VEGF, and the pleural effusion indicators such as PH, glucose, LDH, VEGF and surviving." (PMID 35209915, 2022). "In the univariate analysis, a PS of 2‐4, never smoking, driver mutations including those of EGFR and ALK, LDH ≥ 240 IU/L, CRP ≥ 1 mg/dL, NLR ≥ 4, liver metastasis, brain metastasis, pleural effusion, and steroid use at the commencement of nivolumab treatment were associated with a shorter PFS." (PMID 31880861, 2020). "Interestingly, our result also presented that ALK‐positive patients had significantly lower incidence of pleural effusion than both ALK‐ and EGFR‐negative patients." (PMID 28374971, 2017).
nasopharyngeal carcinoma (108 papers, 2005 to 2026). A carcinoma arising from the nasopharyngeal epithelium. "EGFR overexpression has been reported and implicated in the pathogenesis of many cancers, including nasopharyngeal carcinoma (NPC)." (PMID 39594573, 2024). "Some studies have documented that EGFR is overexpressed in 80%-90% of nasopharyngeal cancers, often resulting in poor survival, possibly associated with resistance to radiation or drugs." (PMID 36814816, 2023). "Three studies investigating 393 nasopharyngeal carcinoma tissue samples reported the association of the expression of p-EGFR and the OS of nasopharyngeal carcinoma patients." (PMID 35060503, 2022). "For studies that reported DFS, EGFR overexpression was associated with worse DFS in patients with nasopharyngeal carcinoma (HR = 2.53, 95% CI [1.84, 3.47], P < .01)." (PMID 35060503, 2022). "Overexpression of epidermal growth factor receptor can be found in more than 80% of patients with locoregionally advanced nasopharyngeal carcinoma and is associated with shorter survival." (PMID 27974693, 2017). "Nasopharyngeal carcinoma (NPC) is an epithelial malignancy usually associated with overexpression of both epidermal growth factor receptor (EGFR) and β-catenin." (PMID 28157708, 2017). "We demonstrated IL-6 modulated iNOS expression via STAT3 and EGFR in EBV-associated nasopharyngeal carcinoma." (PMID 25547488, 2014). "The epidermal growth factor receptor (EGFR) is usually overexpressed in nasopharyngeal carcinoma (NPC) and is associated with pathogenesis of NPC." (PMID 21711528, 2011). "SPINK 6, for instance, has been implicated in promoting nasopharyngeal carcinoma metastasis through direct binding and activation of EGFR, which increases EMT markers like N-cadherin and Snail, reinforcing the role of SPINK–EGFR crosstalk in cancer dissemination." (PMID 40872585, 2025). "The development and progression in 90% nasopharyngeal carcinomas are caused by EGFR." (PMID 29973197, 2018). "FOXQ1 promotes EGFR expression at mRNA and protein levels, mediates the EGFR signaling activity, and increases the metastasis of nasopharyngeal carcinoma (NPC) by inducing vasculogenic mimicry." (PMID 41347087, 2025). "Similar oncogenic roles have been attributed to SPINK 6 in nasopharyngeal carcinoma, where it enhances metastasis by binding to and activating EGFR, amplifying downstream signals responsible for EMT and matrix degradation." (PMID 40872585, 2025). "Nimotuzumab has been approved to be used in combination with radiotherapy for the treatment of EGFR positive stage III/IV nasopharyngeal carcinoma and has the effect of sensitized radiotherapy." (PMID 40335598, 2025). "The results of their network analysis experiments showed that the anti-nasopharyngeal carcinoma effect of CEP was related to eight core targets such as EGFR, AKT1, PIK3CA and mTOR." (PMID 41368570, 2025). "In clinical trials in humans with nasopharyngeal carcinoma, the EGFR-TKI cetuximab in combination with chemotherapeutic agents (carboplatin, cisplatin) and/or radiotherapy resulted in comparably favorable survival times with controllable side effects." (PMID 39268521, 2024). "The stimulation of EGFR by TGFα induces sAPPα secretion, leading to increased cell proliferation and motility in nasopharyngeal carcinoma." (PMID 39332525, 2024). "Regarding correlation between EGFR expression and survival, in human undifferentiated nasopharyngeal carcinomas, a correlation between increased EGFR expression and shorter survival times was found." (PMID 39268521, 2024). "In human nasopharyngeal carcinomas, a correlation between EGFR expression and an advanced tumor stage has been demonstrated." (PMID 39268521, 2024). "The EGFR-TKI icotinib also has a radiosensitising effect in preclinical studies on cell lines of human nasopharyngeal carcinomas and was well tolerated clinically in a phase I study with concurrent intensity-modulated radiotherapy." (PMID 39268521, 2024).
nasopharyngeal carcinoma (continued). "In this context, silencing LACTB can inhibit the metastasis of nasopharyngeal carcinoma by inhibiting ERBB3/EGFR signal transduction and increasing the stability of histone H3." (PMID 38149985, 2023). "In nasopharyngeal cancer treatment, the epidermal growth factor receptor (EGFR) is frequently targeted." (PMID 36814816, 2023). "Meanwhile, the correlation of p-EGFR (the activated form of EGFR) overexpression with the prognosis of nasopharyngeal carcinoma has also been undetermined." (PMID 35060503, 2022). "GE11, an EGFR antagonist peptide, was used to target nasopharyngeal carcinoma which has positive expression of EGFR on its nucleus." (PMID 35600653, 2022). "Two studies including 158 tissue samples removed from patients with nasopharyngeal carcinoma reported the correlation between EGFR expression and the PFS of patients." (PMID 35060503, 2022). "Fifteen studies including 1237 tissue samples removed from nasopharyngeal carcinoma patients reported the correlation of EGFR expression with the OS of nasopharyngeal carcinoma patients." (PMID 35060503, 2022). "In this systematic review and meta-analysis, only 3 studies reported the prognostic effect of p-EGFR on nasopharyngeal carcinoma, among which 3, 1, and 2 studies reported OS, PFS, and DMFS as an outcome, respectively." (PMID 35060503, 2022). "Combining RSL3 and EGFR antibody Cetuximab impairs synergistically the survival of nasopharyngeal carcinoma cells." (PMID 36012290, 2022). "Three studies reported the correlation between the expression of p-EGFR and the prognosis of nasopharyngeal carcinoma, and there are 3, 1 and 2 studies reported OS, PFS, and DMFS as the study outcome, respectively." (PMID 35060503, 2022). "Among all eligible studies, 17 studies reported the correlation between EGFR expression and the prognosis of nasopharyngeal carcinoma, and there were 15, 8, 2, and 5 studies that reported OS, DFS, PFS, and DMFS as the outcome, respectively." (PMID 35060503, 2022). "GE11, an EGFR antagonist peptide, is a potential targeted modification peptide for nasopharyngeal carcinoma." (PMID 35600653, 2022). "We found that nasopharyngeal carcinoma cells (CNE-2) also express a lower level of EGFR compared with CAL33, S18, and S26." (PMID 36012290, 2022). "For studies that reported OS as an outcome, EGFR overexpression indicated worse OS of nasopharyngeal carcinoma patients." (PMID 35060503, 2022). "Five studies containing 496 nasopharyngeal carcinoma tissue samples reported the correlation between EGFR expression and the DMFS of patients." (PMID 35060503, 2022). "Eight studies including 683 nasopharyngeal carcinoma tissue samples reported the correlation of EGFR expression with the DFS of patients." (PMID 35060503, 2022). "GQDs were modified with the targeting polypeptide GE11 to target EGFR which highly expressed on the nucleus of nasopharyngeal carcinoma." (PMID 35600653, 2022). "Subgroup analysis for the expression of EGFR expression with OS of nasopharyngeal carcinoma patients." (PMID 35060503, 2022). "Two studies containing 286 nasopharyngeal carcinoma tissue samples reported the correlation of p-EGFR expression with the DMFS of patients." (PMID 35060503, 2022). "Strong CIP4 expression demonstrated a positive correlation with metastasis of nasopharyngeal carcinoma by activating EGFR signaling." (PMID 34570775, 2021). "It has been reported to act as a functional regulator of nasopharyngeal carcinoma metastasis via the EGFR signaling." (PMID 34133324, 2021). "These suggest that anti-EGFR therapy is an effective strategy in inhibiting VM formation and in preventing metastasis of nasopharyngeal carcinoma." (PMID 33875643, 2021). "Chen and co-workers recently performed anti-EGFR therapy against nasopharyngeal carcinoma by combining Se NPs with gefitinib, which is a human-mouse chimeric antibody blocking EGFR." (PMID 34322025, 2021).